RNU6-364P (RNA, U6 small nuclear 364, pseudogene)
Gene: Small nuclear RNA gene on chromosome 7 (96,341,140 to 96,341,246, forward strand). Ensembl gene ENSG00000207115.
Homologues: Orthologues: chimpanzee U6 (99% identical), macaque U6 (93% identical), mouse Gm26314 (86% identical), pig U6 (85% identical). Paralogues in human: RNU6-35P (90% identical), RNU6-12P (89% identical), RNU6-1316P (89% identical), RNU6-13P (89% identical), RNU6-25P (89% identical), RNU6-32P (89% identical), RNU6-41P (89% identical), RNU6-49P (89% identical), RNU6-1 (88% identical), RNU6-1027P (88% identical), RNU6-1124P (88% identical), RNU6-17P (88% identical), and 1284 more.